CD4 (CD4 molecule)
Diseases named in the same sentence as CD4 in open-access papers (continued):
Sharing a sentence is not in itself a finding about the gene and the disease.
AIDS (continued). "The relatively late initial diagnosis of HIV in AIDS stage may appear to be an exceptional case, given that, with a severely reduced CD4 cell count (below 200 per μl) and with PJ pneumonia as an AIDS‐defining disease at initial diagnosis, our patient falls into the group of ‘late presenters’." (PMID 39624762, 2024). "We hypothesized that, among individuals infected with HIV, treated with ART, and with CD4 counts ≥ 500 cells/mm3, the expansion of CD8+ T cells, reflected in a low CD4/CD8 ratio, may help identify those with persistent innate and adaptive immune activation and at greater risk of non-AIDS events." (PMID 38324873, 2024). "However, all the excluded late presented PWH have AIDS diagnosis within three months of initial HIV diagnosis, and AIDS diagnosis is based on CD4 count < 200 or opportunistic illness and could indicate linkage to healthcare." (PMID 38896338, 2024). "In this context, our data suggest that administration of higher concentrations of MVC could also help to counteract residual chronic immune activation/inflammation that persists throughout the HIV disease, which can accelerate non-AIDS-related events and CD4+ T cell depletion." (PMID 38886484, 2024). "In addition, demographic characteristics and clinical characteristics are examined in relation to AIDS deaths, we focused on whether and to what extent the peak value of CD4 cell count affects mortality in PWH." (PMID 38778273, 2024). "In the analysis of the Korean HIV/AIDS cohort study, we considered a model predicting residual life until the onset of dyslipidemia based on information regarding total cholesterol levels, high-density lipoprotein level, family history of dyslipidemia, age of diagnosis, and CD4 levels." (PMID 38368350, 2024). "Finally, it was reported that a persistent CD8+ T-cell count and, consequently, a low CD4+/CD8+ T-cell ratio in HIV-infected patients, even with CD4+ T-cell count greater than 500 cells/μL, are predictors of non-AIDS events and a greater risk of mortality, which was also observed in this cohort." (PMID 38999501, 2024). "The CD4 counts at diagnosis further decrease if measured around the diagnoses of AIDS-defining conditions, such as Kaposi sarcoma, where 87% of participants have a CD4 count of < 350 cells/μl blood or pneumocystosis with 96% of participants with a CD4 count of < 350 cells/μl blood." (PMID 39476279, 2024). "Furthermore, individuals with suboptimal CD4 recovery tend to exhibit greater immune activation and inflammation compared to those with better CD4 recovery, while PLWH who continue to experience inflammation despite effective cART are at an elevated risk for comorbidities and non-AIDS events." (PMID 39763958, 2024). "Indeed, previous research has revealed an independent positive association between AIDS diagnosis, viral-load non-suppression, low CD4 count and frailty." (PMID 38426187, 2024). "Lower CD4+T lymphocyte counts and slower recovery in CRF01_AE infected individuals contrast with higher counts and faster recovery in CRF07_BC infected individuals, potentially contributing to the increased AIDS prevalence and rapid CRF07_BC expansion in Guangxi." (PMID 38994006, 2024). "Targeting STING1 to prevent CD4 T cell death might be a valid therapy for AIDS." (PMID 39291958, 2024). "Several studies have also confirmed the important role of CD4 cells in helping PWH to defend against tuberculosis, or in measuring the size of their HIV reservoirs and accessing the degree of immune failure, immune activation status, prognosis, and risk of non-AIDS-related inflammation." (PMID 38778273, 2024). "Early initiation of ART, especially when the CD4+ T-cell count is greater than 350/mm3, offers many benefits, including improved immunological recovery and subsequent reductions in both severe AIDS-related and severe non-AIDS-related events, as well as limited establishment of HIV reservoirs." (PMID 38525766, 2024).
AIDS (continued). "HIV predominantly infects CD4 T-lymphocytes, inducing a rapid decline in their numbers that, if not treated, eventually leads to acquired immunodeficiency syndrome (AIDS)." (PMID 39339899, 2024). "Importantly, PWH with incomplete reconstitution of CD4 T lymphocytes are at a greater risk of AIDS-related and non-AIDS-related morbidity and mortality." (PMID 39287441, 2024). "Additionally, the death of the CD4 cells during the AIDS phase triggers the release of intracellular zinc, and this event could also contribute to changes in the serum isotopic ratios." (PMID 37894953, 2023). "Being a farmer, being a merchant, having additional chronic diseases, having anxiety, having CD4 count of 200–499 cell/mm3, being stigmatized, and having poor sleep hygiene were factors that had an association with poor sleep quality among people living with HIV/AIDS." (PMID 37359994, 2023). "Moreover, the CD4:CD8 ratio reflects T-cell activation, innate immune activation, and the presence of an immunosenescent T-cell phenotype; indeed, a low CD4:CD8 ratio has been associated with non-AIDS-defining events and mortality." (PMID 37243208, 2023). "However, we point out that while CD4 count is still the gold standard for evaluating immune function in HIV/AIDS patients, utilizing TLC as a substitute clinical measure in a constrained situation can offer insightful information for disease monitoring and response assessment." (PMID 37893544, 2023). "Sirt1 also contributes to the regulation of the amplification of human immunodeficiency virus 1 (HIV1), which infects CD4-carrying cells, in particular T helper cells, and thereby facilitates opportunistic infections and the development of acquired immunodeficiency syndrome (AIDS)." (PMID 37109478, 2023). "Additionally, considerable information regarding the stage of HIV/AIDS of patients—CD4 count and viral load data—was only available in a small subset of PLWH, and therefore, could not be assessed in this cohort." (PMID 38005919, 2023). "Therefore, it remains controversial whether the CD4/CD8 ratio or CD8 count provides additional value to CD4 count in predicting non-AIDS events." (PMID 37639938, 2023). "However, data on its ability to predict non-AIDS events, beyond that of CD4, are inconclusive." (PMID 37639938, 2023). "However, a substantial proportion of patients (i.e., reaching up to 50% also in high-income countries) are still being diagnosed with HIV at low CD4 counts or at the time of AIDS occurrence, suggesting that efforts to ensure a timely diagnosis of HIV are still needed." (PMID 37243208, 2023). "On the contrary, PLWH with low CD4 + T-cell counts, detectable viremia, and/or previous AIDS were found to have weaker and less durable humoral and T-cell responses to mRNA vaccines [95•, 96••, 98•, 99, 100, 101•], suggesting that they may benefit from additional vaccine doses." (PMID 36680700, 2023). "In this study involving 3073 HIV patients, it was found that the presence of the APOBEC3G exon 4 variant allele H186R was associated with accelerated progression to AIDS and a notable decline in CD4+ T-cell counts, when compared to individuals who did not possess this particular polymorphism." (PMID 37376660, 2023). "In addition, it may be related to the fact that the proportion of co-receptor CXCR4 of CD4 + T cells in AIDS patients infected with CRF01_AE is significantly higher than those observed in patients infected with other subtypes." (PMID 36539633, 2023). "Because systemic cryptococcosis commonly occurs in AIDS patients with low CD4+ T cell count, we tested whether vaccinating hosts with an already low CD4+ T cell count with either the heat-killed or the short-lived ZNF2oe strain will provide protection against otherwise lethal cryptococcosis." (PMID 37338404, 2023). "In addition, a lower CD4-cell count results in a higher risk for opportunistic infections and AIDS-defining malignancies, including Kaposi’s sarcoma, non-Hodgkin lymphoma, and cervical cancers." (PMID 36753495, 2023).
AIDS (continued). "Furthermore, older age, multimorbidity, polypharmacy, diagnosis of acquired immunodeficiency syndrome (AIDS), and low current CD4+ cell count are predictors of frailty." (PMID 37983204, 2023). "Therefore, it may be more appropriate to up-regulate CD4+ T cell count to ≤200 pieces/μL for the prophylactic treatment of NTM disease in patients with HIV/AIDS in China." (PMID 37651639, 2023). "In line with our data, the Multicenter AIDS Cohort Study showed that HLA-A24 was frequent in rapid CD4+ cells decliners, supposing that it might be a factor involved in HIV-1 disease progression; as evidence of the unfavorable impact of HLA-A24 antigen, it is rare in LTNPs." (PMID 35290394, 2022). "Thus, the current international guidelines recommending that prompt or even immediate ART initiation on the day of HIV positivity diagnosis is of great importance to individuals living with HIV before they have markedly decreased CD4 + T cell counts and progression to AIDS." (PMID 35135485, 2022). "We propose that the rs16855458 in XRCC5 intron may regulate the transcription and expression of the XRCC5 by alternative splicing, which interacts with HIV-1 to promote its integration and translation, leading to the decrease in the CD4+ T lymphocyte count and the AIDS acceleration." (PMID 36312587, 2022). "Thus, ART (i) can reduce HIV viral RNA loads to below detectable levels, (ii) can increase the circulating number of CD4+ T-cells, (iii) can reduce the incidence of AIDS-related disease and/or death, and (iv) can effectively prevent the transmission of HIV to uninfected people." (PMID 35185920, 2022). "HIV is a retrovirus that destroys activated CD4 cells, which play a major role in the regulation of humoral and cell-mediated immune responses, leading to infection with opportunistic pathogens that usually appear when the CD4 cell count declines below 200 cells per μl of blood as in AIDS patients." (PMID 34983416, 2022). "In the case of acute HIV-1 subtype B and C infections, the pro-inflammatory “cytokine storm” activation contributes to CD4+ T cell lymphopenia and prevention of IL-2 producing memory CD4+ and CD8+ T cells, which lead to the development of the acquired immune deficiency syndrome (AIDS)." (PMID 36313221, 2022). "Furthermore, CD4+ T cells border the periphery of pulmonary granulomas in HIV+ individuals receiving antiretroviral therapy, but they are lost in individuals with advanced HIV/AIDS, suggesting that CD4+ lymphocytes may be involved in granuloma maintenance." (PMID 35587201, 2022). "In acquired immunodeficiency syndrome-diagnosed patients, we found a significant increase in the CD4+ T-cell count at week 48 (log OR = 41.7, P = .0038), but no significant changes in the CD8+ T-cell count (log OR = –23.4, P = .54)." (PMID 35713430, 2022). "The next year, Professor Théry C found that dendritic cell-derived exosomes could indirectly activate CD4+ T cells and amplify the initiation of primary adaptive immune responses, and this paper laid the foundation for the study of dendritic cells in AIDs." (PMID 35935932, 2022). "Particularly, a CD4/CD8 ratio ≤ 0.4 has been found to be associated with T cell activation, innate immune activation and an immunosenescent phenotype, and to predict serious non-AIDS events, even in virologically suppressed persons with absolute CD4 count > 500/μL." (PMID 35428209, 2022). "In addition to CD4+ T cell decline and high levels of secondary viremia, another characteristic of AIDS is microbial invasion with the collapse of immunity, which can easily lead to a strong inflammatory response, thus promoting the replication of HIV and accelerating the progression of disease." (PMID 35458449, 2022). "One major characteristic of this virus is to attack the CD4+ T lymphocytes and cells from the monocyte/macrophage lineage that leads to the acquired immunodeficiency syndrome (AIDS) if the virus is not appropriately treated." (PMID 35146953, 2022).
AIDS (continued). "Thus, our aim was to estimate the association of cumulative percentage of time with CD4 <200 cells/μL on mortality and AIDS- and non-AIDS-related comorbidities among ART-initiators with VS in the CCASAnet cohort during 2000-2019." (PMID 35602655, 2022). "Besides, we found that the risk of clinical progression, and specifically of AIDS events, was higher when the CD4/CD8 ratio was ≤ 0.4 over time for both non-late and late or advanced presenters." (PMID 35428209, 2022). "Age, work status, CD4 at time of diagnosis, current CD4 level, duration of treatment, WHO clinical stage at treatment initiation, and taking Cotrimoxazole prophylaxis were associated with HRQoL among people living with HIV/AIDS on HAART were associated with HRQoL." (PMID 33667245, 2021). "The causes of this immunological failure remain unclear, and no treatment is available to improve CD4+ T-cell count restoration and health of InRs, who are at higher risk of AIDS and non-AIDS morbidity and mortality." (PMID 35222352, 2021). "The absence of CD4+ is important because it leads to profound immunodeficiency, being involved in various autoimmune disorders, and acquired immune deficiency syndrome (AIDS)." (PMID 34948375, 2021). "Thus, the combination of cART and Jianpi Yishen decoction may improve symptoms in asymptomatic patients with AIDS and increase CD4+ T cell counts." (PMID 34881074, 2021). "Thus, potential direct in vivo delivery of such an antiviral designer recombinase using CD4-Nb-targeted AAV gene vectors may ultimately enable the clinical development of a scalable curative therapy for HIV/AIDS." (PMID 34928979, 2021). "Additionally, our analysis was limited to factors at last paediatric care visit which were associated with AIDS/mortality, while future analyses might take a time‐updated approach to ART, viral load and CD4 measures." (PMID 33939876, 2021). "In the absence of ART, patients progress to acquired immune deficiency syndrome (AIDS), which is characterized by a rise in viremia and compromised function of CD4+ T cells, which are the primary targets of HIV-1 replication." (PMID 33647028, 2021). "The hallmarks of B bronchiseptica infections in patients with HIV/AIDS are a respiratory syndrome, most frequently characterized as an atypical pneumonia with persistent cough, in individuals with advanced immune suppression as evidenced by substantial CD4 lymphocyte depletion." (PMID 34941094, 2021). "Moreover, CPP data showed that in the three-year period from 2016–2018, Ukrainian adults ≥50 years were significantly more likely to have AIDS (CD4<200) at diagnosis (43.8%) than 25–49 years (29.4%) and 15–24 years (13.2%) (p<0.001); this relationship remained similar for each year." (PMID 34591848, 2021). "In adjusted models, only older age and low CD4 cell count at KS diagnosis were significantly associated with mortality risk, underscoring the importance of early HIV diagnosis and treatment to improve not only rates of AIDS‐defining conditions such as KS but also their outcomes." (PMID 33405281, 2021). "Using the World Health Organization (WHO) HIV/AIDS revised clinical staging, 354 out of 6235 (5.7%) patients met the criteria for advanced disease, 115 of which were defined by immunological criteria (CD4 cell count <350 μL), and 239 by clinical criteria (clinical Stage 3 or 4)." (PMID 33808066, 2021). "Most infected patients, called progressors, usually develop AIDS after 8–10 years, but a small group of people, known as long-term non-progressors (LTNPs), remains asymptomatic for more than ten years and are characterized by high CD4+ cell counts (more than 500 cells/ml)." (PMID 34025935, 2021). "When LP was defined as CD4 count <350 cells/μL or an AIDS diagnosis within 24 weeks of enrolment, the percentage of individuals who could not be classified as late presenters or non-late presenters was 6.1%, while it was around 4% when the window was modified to 4, 12 or 48 weeks." (PMID 33882093, 2021).
AIDS (continued). "Furthermore, it is worrying that, from the total of participants, 39% had a CD4/CD8 ratio < 0.30, considered as a marker of profound immune damage, with a high risk of non-AIDS-defining events or death; plus, only 7.8% of all patients had an optimal CD4/CD8 ratio of ≥ 0.8 (data not shown)." (PMID 34556049, 2021). "The IGRA test also studied in HIV patients in recent years and reported that HIV-1-infected patients with an indeterminate IFN-γ release assay result at baseline were at significantly higher risk of developing AIDS manifestations other than tuberculosis regardless of CD4+ T cell count." (PMID 34367385, 2021). "Widowed marital status, poor medication adherence, low social support, CD4 count ≤ 200, having adverse drug reactions, presence of opportunistic infections, and perceived social stigma were significantly associated with depression among adult HIV/AIDS patients at ART clinics in Ethiopia." (PMID 34721902, 2021). "Similarly, in another analysis of over 84,000 individuals from 23 countries in Europe presenting for HIV care between 2000 and 2011, late presentation, defined as HIV diagnosis with a CD4 count < 350/mm3 or an AIDS diagnosis within 6 months of HIV diagnosis, was observed for 54%." (PMID 33607975, 2021). "Furthermore, a few studies have reported that there is an U-shaped relationship between CD8 counts and all-cause mortality, and a low CD4/CD8 ratio is associated with increased AIDS- or non-AIDS-related morbidity and mortality in patients on ART after adjusting the CD4 count." (PMID 33131455, 2020). "Reduced CD4/CD8 ratio has been found to be a marker for immune dysregulation and activation in the setting of HIV infection that has been associated with an increased risk for non‐AIDS related morbidity and mortality, including age‐related inflammation and cardiovascular disease." (PMID 32949118, 2020). "The results in this study also revealed that serious NADEs could occur in cART-naive AIDS patients with CD4 > 350 cells/ul, which demonstrated that serious NADEs could occur in cART-naive patients with higher CD4 levels and earlier screening was necessary among these patients." (PMID 33351812, 2020). "HIV is a retrovirus that infects CD4 immune cells, leading to immunodeficiency and ultimately Acquired Immunodeficiency Syndrome (AIDS) if not treated." (PMID 33304036, 2020). "Although there were inconsistencies regarding these risk-minimizing strategies, higher CD4 count, lower viral load, not at AIDS stage 3 or 4, timed unprotected sex and using ART for a longer period were the safe conception strategies that were discussed between WLHIV and their HCPs." (PMID 32807202, 2020). "In summary, HIV/AIDS-associated disruption of oral, intestinal and genital epithelia is still an issue with antiretroviral therapy, possibly because of residual HIV infection of intramucosal CD4 + T lymphocytes, macrophages, Langerhans/dendritic cells and/or HIV/AIDS-initiated chronic inflammation." (PMID 32862519, 2020). "Besides the absolute CD4 T-cell count, the CD4+/CD8+ ratio and the CD4 T-cell percentage (CD4+%) predicts the risk of AIDS and non-AIDS events." (PMID 31945066, 2020). "CD4+ T-cells play a critical role in immune protection, and low counts in HIV-1 patients were strongly associated with progression to acquired immune deficiency syndrome (AIDS), which made this disease an ideal target for attempting treatment using a gene edited cell therapy." (PMID 32034584, 2020). "Furthermore, prednisolone slows the loss of CD4+ T cells and inhibits apoptosis of activated CD4+ T cells in ARV-treated patients and during structured therapy interruption, hindering the progression to AIDS." (PMID 33178456, 2020). "However, almost 20% patients have deficient immune reconstitution of CD4+ T-cells, which make them more susceptible to develop non-AIDS and AIDS comorbidities." (PMID 33071649, 2020).